SNAP25 (synaptosome associated protein 25)
Description:
t-SNARE involved in the molecular regulation of neurotransmitter release. May play an important role in the synaptic function of specific neuronal systems. Associates with proteins involved in vesicle docking and membrane fusion. Regulates plasma membrane recycling through its interaction with CENPF.
Synonyms: SNAP-25; SUP; SNAP; RIC-4; RIC4; SEC9; bA416N4.2; dJ1068F16.2; CMS18; DEE117
Tractability: Small molecule: a structure with a bound ligand is known. Antibody: its Gene Ontology location is reachable by antibodies, with high confidence; UniProt places it where antibodies can reach, with medium confidence; the Human Protein Atlas places it where antibodies can reach. PROTAC: ubiquitination databases record sites on it; its protein half-life has been measured. Other modalities: an approved drug acts on it.
Target class: Other cytosolic protein
Gene: Protein-coding gene on chromosome 20 (10,172,395 to 10,308,258, forward strand). Ensembl gene ENSG00000132639.
Subcellular location: Cytoplasm, perinuclear region; Cell membrane; Synapse, synaptosome; Photoreceptor inner segment
Subcellular location (Human Protein Atlas): Plasma membrane; Vesicles
Pathways (Reactome):
Neuronal System: Acetylcholine Neurotransmitter Release Cycle; Dopamine Neurotransmitter Release Cycle; GABA synthesis, release, reuptake and degradation; Glutamate Neurotransmitter Release Cycle; Norepinephrine Neurotransmitter Release Cycle; Serotonin Neurotransmitter Release Cycle
Disease: Toxicity of botulinum toxin type A (botA); Toxicity of botulinum toxin type C (botC); Toxicity of botulinum toxin type E (botE)
Immune System: Neutrophil degranulation; Other interleukin signaling
Metabolism: Regulation of insulin secretion
Sensory Perception: Sensory processing of sound by inner hair cells of the cochlea
Gene Ontology:
Molecular function: lipid binding; protein binding; syntaxin-1 binding; calcium-dependent protein binding; SNAP receptor activity; SNARE binding; voltage-gated potassium channel activity
Biological process: vesicle fusion; chemical synaptic transmission; exocytosis; neurotransmitter secretion; neurotransmitter uptake; regulation of insulin secretion; synaptic vesicle exocytosis; synaptic vesicle fusion to presynaptic active zone membrane; synaptic vesicle priming; membrane fusion; potassium ion transmembrane transport; presynaptic dense core vesicle exocytosis; regulation of establishment of protein localization; regulation of neuron projection development
Cellular component: BLOC-1 complex; cytoplasm; cytoskeleton; SNARE complex; synaptobrevin 2-SNAP-25-syntaxin-1a complex; vesicle; cytosol; growth cone; membrane; neuron projection; photoreceptor inner segment; plasma membrane; presynaptic membrane; specific granule membrane; synaptic vesicle membrane; synaptobrevin 2-SNAP-25-syntaxin-1a-complexin I complex; tertiary granule membrane; voltage-gated potassium channel complex; axon; cell cortex; glutamatergic synapse; perinuclear region of cytoplasm; ribbon synapse; somatodendritic compartment; synapse; and 2 more
Genetic constraint (gnomAD): Loss-of-function variants: 2 observed, 21.68 expected, observed/expected ratio (o/e) 0.0923, 90% interval 0.037 to 0.29. The synonymous counts are far from expectation, so gnomAD's model fits this gene poorly and the ratio says little. Missense variants: 107 observed, 243.7 expected, observed/expected ratio (o/e) 0.44, 90% interval 0.37 to 0.52. Synonymous variants: 49 observed, 78.82 expected, observed/expected ratio (o/e) 0.62, 90% interval 0.49 to 0.79.
Gene-disease validity (ClinGen):
ClinGen rates the evidence that SNAP25 causes each of these diseases.
genetic developmental and epileptic encephalopathy (autosomal dominant): Definitive. A complex neurodevelopmental disorder characterized by a range of developmental delays and epileptic encephalopathy phenotypes.
Homologues: Orthologues: chimpanzee SNAP25 (100% identical), macaque SNAP25 (100% identical), mouse Snap25 (96% identical), pig SNAP25 (96% identical), guinea pig SNAP25 (95% identical), zebrafish snap25a (93% identical), tropical clawed frog snap25 (89% identical), zebrafish snap25b (89% identical), rat Snap25 (86% identical), dog SNAP25 (85% identical), rabbit SNAP25 (68% identical), Drosophila melanogaster Snap25 (56% identical), and 2 more. Paralogues in human: SNAP23 (60% identical), SNAP47 (23% identical), SNAP29 (22% identical).
Diseases named in the same sentence as SNAP25 in open-access papers:
SNAP25 is named in the same sentence as 170 diseases in open-access papers, as found by Europe PMC text mining. Sharing a sentence is not in itself a finding about the gene and the disease. The quoted sentences say what the papers report.
schizophrenia (47 papers, 2012 to 2025). A major psychotic disorder characterized by abnormalities in the perception or expression of reality. "Previous studies have tied palmitoylation to synaptic plasticity, with aberrant modification of proteins like PSD‐95 and SNAP‐25 linked to neurotransmitter dysregulation in schizophrenia." (PMID 40842128, 2025). "Changes in SNAP-25 activity are associated with cognitive deficits found in several disorders such as attention deficit hyperactivity disorder and schizophrenia." (PMID 35309682, 2022). "It was also already reported that alterations in gene expression of SNAP25 in mammals are associated with schizophrenia-like behavior, and sequence variations in the SNAP25 locus are associated with attention-deficit/hyperactivity disorder (ADHD)." (PMID 33799572, 2021). "Case-control GWAS studies of individuals with schizophrenia have recently indicated common alleles within transcripts of the C4 genes, which encodes a complement component 4 protein, and SNAP25, a vesicle fusion protein, contribute to risk of disease." (PMID 31844109, 2019). "Several genes showing enhanced THC sensitivity across development, notably pyramidal-enriched Pacsin1, as well as Clu and Snap25, are also implicated in psychiatric diseases such as schizophrenia and mood disorders." (PMID 30283037, 2019). "Precise control of Snap25 levels by miR-210-5p can be a potential medical benefit for Snap25 associated diseases such as attention deficit hyperactivity disorder, schizophrenia, early-onset of bipolar disorders and so on." (PMID 30483048, 2018). "Several studies have associated reduced expression of synaptosomal-associated protein of 25 kDa (SNAP-25) with schizophrenia, yet little is known about its role in the illness." (PMID 29318050, 2017). "Amongst the schizophrenia-susceptibility genes with the most prominent TTTPs were those with established synaptic functions, including Rgs4, Snap25, Kalrn, Htr2a and Nrg1." (PMID 28893375, 2017). "TMPAP also colocalizes and interacts with snapin, which directly binds SNAP-25, a protein that has been linked to schizophrenia in genetic, pathological and functional studies." (PMID 24846136, 2014). "Recent human genetic studies have discovered associations between SNAP-25 and various psychiatric and neurological disorders, such as schizophrenia, attention-deficit/hyperactivity disorder (ADHD), and epilepsy." (PMID 23497716, 2013). "Previous reports have shown that SNAP-25 KI mice display increases in anxiety-like behaviors and that the SNAP-25 gene is associated with various neuropsychiatric disorders, such as schizophrenia, ADHD, and epilepsy." (PMID 23497716, 2013). "Immunoprecipitation studies have demonstrated an increased binding affinity of SNAP25 to the Munc18-1 and Cplx1 proteins in the brain of patients with schizophrenia, which may underlie the formation of the aberrant SNARE complex during the disease." (PMID 36430976, 2022). "Disruptions of the SNAP25 gene could cause dysregulated circadian rhythm in the schizophrenia-related mouse model." (PMID 35873241, 2022). "The SNAP-25 gene may be associated with clinical response and weight gain in antipsychotic treatment of schizophrenia." (PMID 30093869, 2018). "However, the SNAP-25 locus (Chr: 20p12.3-11) has been implicated in a meta-analysis of genome-wide linkage scans of schizophrenia." (PMID 24846136, 2014). "Notably, SNAP-25 has been implicated in schizophrenia from genetic, pathological, and functional studies." (PMID 22264613, 2012). "Several studies investigated the relationship between SNAP-25 gene polymorphism and personality disorders, schizophrenia, and attention deficit and hyperactivity disorder; these studies reported that the SNAP-25 gene might influence development of these disorders." (PMID 24885975, 2014).
schizophrenia (continued). "Additionally, it has been suggested that polymorphisms in ADRA2A (alpha-2A adrenergic receptor), DRD3 (dopamine receptor D3), DBH (dopamine β-hydroxylase) and SNAP-25 (25 kDa synaptosomal-associated protein) are individually or collectively risk factors for schizophrenia." (PMID 25408901, 2013). "Previous studies found that genetic polymorphisms of SNAP-25 are correlated with the progression of AD and PD; in addition, elevated levels of SNAP-25 proteins are exhibited in schizophrenia patients and bipolar disorders." (PMID 39551143, 2024). "This assumption was confirmed by the work of Ramos-Miguel and colleagues, who showed the presence of homotetrameric SNAP25 aggregates in autopsy samples of the orbitofrontal cortex of patients with schizophrenia and depression." (PMID 36430976, 2022). "Alterations of SNAP25 expression have been observed in several psychiatric conditions, such as schizophrenia and bipolar disorder." (PMID 36430976, 2022). "The SNAP-25 gene has been associated with distinct brain diseases, including attention deficit hyperactivity disorder (ADHD), schizophrenia and bipolar disorder—which is possibly due to its encoded protein is involved in synaptic functions." (PMID 35873241, 2022). "Some studies suggest that Snap25 imbalances, or changes in expression of SNAP25-a and SNAP25-b isoforms, contribute to ADHD and schizophrenia, as well as alcohol use disorder (AUD) and smoking risk." (PMID 34064652, 2021). "SNAP-25 gene has been associated with several human psychiatric disorders, including attention-deficit/hyperactivity disorder (ADHD), schizophrenia, and bipolar disorder." (PMID 34638726, 2021). "The resultant mice exhibited schizophrenia-like behaviors accompanied by the reduction of SNAP-25 expression in the cortical and hippocampal regions." (PMID 34206873, 2021). "The variability of SNAP-25 protein levels in different brain areas has been proposed to contribute to the manifestations of variable behavioral symptoms in some schizophrenia patients." (PMID 34638726, 2021). "Nine studies comprising 139 patients with schizophrenia and 138 controls measured SNAP-25 levels in frontal cortex (approximating BAs 9, 10, 46, 47)." (PMID 29511299, 2019). "SNAP-25 protein levels were found significantly decreased in one of two studies, while mRNA levels were unchanged in one study in schizophrenia." (PMID 29511299, 2019). "In the hippocampus, three studies examined SNAP-25 protein levels, two of which found a significant reduction in schizophrenia." (PMID 29511299, 2019). "Our findings provide in vivo functional evidence showing a critical role of SNAP-25 dysfunction on synaptic transmission, which contributes to the developmental of schizophrenia." (PMID 29318050, 2017). "We showed that SNAP-25 conditional knockout (cKO) mice exhibited typical schizophrenia-like phenotype." (PMID 29318050, 2017). "Growing evidence suggests that SNAP-25 is involved in neuropsychiatric disorders, such as schizophrenia, attention-deficit/hyperactivity disorder, and epilepsy." (PMID 23497716, 2013). "Abnormal anxiety-like behaviors are found in other animal models of schizophrenia, such as forebrain-specific calcineurin KO, Mus musculus microtubule-associated protein 6 (Mtap6 or STOP) KO, Shn-2 KO, or SNAP-25 KI mice." (PMID 23688147, 2013). "Altered expression patterns were identified in SNAP-25 KI mice in 18 of these top 42 candidate genes for schizophrenia." (PMID 23497716, 2013). "Two core SNARE proteins, the synaptosomal-associated protein of 25 kDa (SNAP25) and the vesicle-associated membrane protein (VAMP1, also known as synaptobrevin), were both significantly down-regulated in schizophrenia." (PMID 22558445, 2012). "SNAP-25 aggregates may also form in vivo, as they were observed in the brain tissues of schizophrenia patients." (PMID 39551143, 2024).
schizophrenia (continued). "SNAP25 has long been associated with attention deficit hyperactivity disorder and schizophrenia; while there have been almost no reports related to malignant tumours." (PMID 38291183, 2024). "SNAP23, SNAP25, SNCA, and GAP43, present in the presynaptic membrane, play essential roles in neurotransmitter release and plasticity and are associated with schizophrenia." (PMID 35062349, 2022). "Moreover, in a major mouse model of schizophrenia, in which a human variant of the disrupted in schizophrenia (DISC1) gene is expressed transgenically, the hDISC1 mouse, Snap25 levels are concomitantly decreased." (PMID 35724379, 2022). "Interestingly, postmortem studies on schizophrenia patients’ brains have shown that altered protein levels of SNAP-25 are specific to regions of the brain." (PMID 34638726, 2021). "For example, SNAP-25 protein expression is reduced in the hippocampus, and anterior prefrontal cortex, whereas its expression is increased in the cingulate cortex and dorsolateral and medial prefrontal cortex (Broadman’s area 9) of schizophrenia patients." (PMID 34638726, 2021). "For instance, SNAP25 (synaptosome-associated protein 25) is the core component of the soluble N-ethylmaleimide fusion protein attachment protein receptor (SNARE) and is associated with brain-related diseases, such as autism and schizophrenia." (PMID 34691153, 2021). "For example, miR-153 regulates Snap25, Vamp2, Snca, Trak2, Bsn and Pclo genes at the mRNA level; miR-137 inhibits complexin-1, Nsf and Syt1 in mouse model of schizophrenia; miR-34c targets VAMP-2 and miR-135a binds the complexin-1 and complexin-2 genes in the amygdala." (PMID 32252776, 2020). "SP1 can regulate gene FE65, which act as a ligand of Alzheimer’s disease amyloid precursor protein, and SP1 can promote the expression of SNAP-25, which is involved in the pathogenesis of neuropsychiatric disorders, including schizophrenia, attention deficit hyperactivity disorder and AD." (PMID 31422384, 2019). "Interestingly, this effect is supported by studies that show low post-mortem levels of forebrain SNAP-25 in several neuropsychiatric disorders like bipolar disorder, schizophrenia and MDD." (PMID 31480244, 2019). "It has been shown in many previous papers that SNAP-25 is involved in psychiatric disorders, such as schizophrenia, attention-deficit/hyperactivity disorder and autism spectrum disorders, in mice and humans and that stress increases the SNAP-25 phosphorylation." (PMID 28801590, 2017). "Notably, even in schizophrenia, where the SNAP-25 levels are significantly lower in the hippocampus and in the frontal lobe Broadman's area 10, an association between the rs1051312 polymorphism of the Snap-25 gene and cognitive dysfunctions was reported." (PMID 27047369, 2016). "Moreover, translational convergent functional genomics has demonstrated that SNAP-25 is one of top 42 candidate genes for schizophrenia." (PMID 23497716, 2013). "Although no definitive causal links between SNAP-25 mutations and schizophrenia have been proven, there are a considerable number of studies that demonstrate an association between this gene and mental health." (PMID 22264613, 2012). "Among the genes that play a role in synaptic plasticity, the SNAP-25 (synaptosomal-associated protein of 25 kDa) gene has been largely associated with common neuropsychiatric disorders, such as attention deficit/hyperactivity disorder (ADHD), bipolar disorders, and schizophrenia." (PMID 37762342, 2023). "Similarly, the sensorimotor gating deficits observed in Bdr mice can be explained as a schizophrenia‐like phenotype, as similar abnormalities in pre‐attentive processing have been observed in human patients with schizophrenia, linking Snap25 activity to cognitive functioning." (PMID 35724379, 2022). "Additionally, a decrease of SNAP25 was found in the hippocampus of patients with schizophrenia." (PMID 31890034, 2019).
schizophrenia (continued). "It is suggested that a SNAP-25 cKO mouse, a valuable model for schizophrenia, could address questions regarding presynaptic alterations that contribute to the etiopathophysiology of SZ and help to consummate the pre- and postsynaptic glutamatergic pathogenesis of the illness." (PMID 29318050, 2017). "The SNAP-25 gene has been associated with distinct brain diseases, including Attention Deficit Hyperactivity Disorder (ADHD), schizophrenia and bipolar disorder, indicating that the protein may act as a shared biological substrate among different “synaptopathies”." (PMID 27047369, 2016). "In this paper, a forebrain glutamatergic neuron-specific SNAP-25 knockout mouse model was constructed and studied to explore the possible pathogenetic role of SNAP-25 in schizophrenia." (PMID 29318050, 2017). "Elevated expression of SNAP-25 produced increased levels of secreted glutamate with cognitive deficits similar to those observed in ADHD and schizophrenia." (PMID 23451149, 2013). "Accumulating evidence suggests that SNAP-25 misregulation plays a role in numerous human disease states including ADHD, schizophrenia, bipolar I disorder, Huntington’s disease, Alzheimer’s disease, and diabetes." (PMID 23451149, 2013). "Therefore, this study supports the finding that this allelic variation of SNAP25 has a functional effect on modulating the development and plasticity of the prefrontal-limbic network, which may increase vulnerability to both early onset bipolar disorder and schizophrenia." (PMID 37635807, 2023). "Schizophrenia-like behavioral impairments in prefrontal downregulation of Piccolo are probably not mediated by observed reduction of SNAP-25." (PMID 34206873, 2021). "The three mRNA studies of SNAP-25 in the frontal cortex showed non-significant reductions or no changes in mRNA levels in schizophrenia." (PMID 29511299, 2019). "While the candidate genes used to construct this network were selected using evidence for disease implication derived from two different approaches, the network includes many additional genes of potential relevance to schizophrenia (e.g., GRIA2, GRIN1, GRIN2B, HOMER1, PICK1, and SNAP25)." (PMID 25484875, 2014). "Finally, there are additional links between SNAP-25 and human cognitive endophenotypes and multiple reports of altered SNAP-25 expression in both patients and mouse models of schizophrenia." (PMID 22264613, 2012). "In addition, the main components of the SNARE complex (SNAP25, syntaxin, VAMP) are known to interact abnormally with the ancillary proteins that are involved in the process of presynaptic binding and release in patients with schizophrenia." (PMID 36430976, 2022). "Indeed, optimal levels of SNAP-25 are important for neurotransmission, and changes in SNAP-25 expression may contribute to the pathophysiology of various diseases, including Alzheimer's disease, schizophrenia, autism, and ADHD." (PMID 35069142, 2021).